RUNX2 (RUNX family transcription factor 2)
Diseases named in the same sentence as RUNX2 in open-access papers (continued):
Sharing a sentence is not in itself a finding about the gene and the disease.
cancer (continued). "Increasing evidence has highlighted the importance of RUNX2 in a variety of cancers." (PMID 33365318, 2020). "Importantly, the bone sialoprotein (IBSP) and osteopontin (SPP1) coding genes, which are regulated by RUNX2, play important roles in bone metastases derived from osteotropic cancers." (PMID 32204402, 2020). "This gene is intriguing in that it is downstream of RUNX2, a master regulator of bone development and ossification, and a high expression has been correlated to a faster disease progression in a number of cancers (i.e., colon, prostate, breast, head, and neck) due to the overexpression of PTHLH." (PMID 32290096, 2020). "To date, the role of RUNX2 in carcinogenesis and cancer progression remains unclear and may be tissue- and context-dependent." (PMID 33313404, 2020). "RUNX2 influences a number of genes involved in cancer progression, such as BSP, MMPs, or VEGF26." (PMID 32102992, 2020). "Overall, our data provide new insights into the molecular mechanisms controlling RUNX2 in cancer and consolidate the rationale for the use of HDACi as potential pharmacological strategy to counteract the pro-oncogenic program controlled by RUNX2 in cancer cells." (PMID 31395086, 2019). "Gene RUNX2 is identified by B2 as important for five cancer types." (PMID 31405076, 2019). "As many other factors crucial for embryogenesis, RUNX2 is often aberrantly reactivated in cancer." (PMID 31395086, 2019). "In addition to this mechanism, which is transversal to different types of cancers, we also showed that cancer cells characterized by peculiarly high RUNX2 levels (TPC1) rely on the additional activity of HDAC6." (PMID 31395086, 2019). "The regulatory mechanisms that control the activity of the P2 promoter and that lead to RUNX2 re-expression in cancer have been unknown for long time." (PMID 31395086, 2019). "The mechanisms leading to RUNX2 expression in cancer has only recently began to emerge." (PMID 31395086, 2019). "In conclusion, our study suggests that RUNT domain may be an ideal oncotarget in melanoma cancer cells as well as in a variety of other common cancers, in which RUNX2 has been found abnormally expressed." (PMID 30463392, 2018). "Thus, WWOX suppressor activity relies on its binding capacities to known cancer-related proteins such as p73, deltaNp63, AP2γ, c-jun, Erbb4, c-Met, RUNX2, and Dvl-2." (PMID 30285739, 2018). "RUNX2 is also recognized as a marker of mesenchymal stem cells found in tumors and has been proven to participate in various signaling pathways involved in cancer growth progression." (PMID 28938538, 2017). "Quite interestingly, genes and associated interaction partners that were downregulated upon Hic-5 KD comprised members and/or associated partners of the TGFβ pathway (including TGF-β2, TGFβR, TGFβRII, FGF2, CTGF, FGFR, SRC, RUNX2 and CDH2), that are commonly implicated in inducing EMT in cancer." (PMID 29137281, 2017). "As a result, RUNX2 plays an important role in the process of cancer development." (PMID 28938538, 2017). "Along with Robo1, other molecules like receptor protein tyrosine phosphatase alpha (RPTPα), myocyte enhancer factor 2D (MEF2D), and runt-related transcription factor 2 (RUNX2) are post-transcriptional target molecules of miR-218, which are known to induce cancer metastasis like MACC1." (PMID 27462788, 2016). "The interplay between RUNX2 and estrogen signaling was reported in several cancers." (PMID 26404249, 2015). "The major functions reported for the genes up-regulated by Runx2 belonged to cancer progression." (PMID 26575035, 2015).
cancer (continued). "Recently, it has been shown that increased residence of RUNX2 at mitotic chromosomes may reflect its epigenetic function in “bookmarking” of target genes in cancer cells." (PMID 25619880, 2015). "It is now believed that RUNX2 plays a role in cell cycle promotion in various cancers." (PMID 26404249, 2015). "Our TMA results indicated that high-level RUNX2 expression could be a marker for a subset of cancers with poor prognosis." (PMID 24626992, 2014). "The differential Akt regulation by Runx2 in non-invasive and invasive cancer cells could be due to altered Runx2 phosphorylation in invasive cells." (PMID 24479521, 2014). "Taken together, our findings show that Runx2 promotes cancer cell survival by directly inducing subunits of mTORC2 kinase complex of the Akt signaling pathway and further suggest Runx2 inhibition as a potential therapeutic strategy in combination with currently available PI3K/Akt/mTOR inhibitors." (PMID 24479521, 2014). "Many of the 12q fusion genes produced chimeric proteins or disrupted cancer-associated genes such as RUNX2, CCND3, and LRP1, indicating that some of the fusions may contribute to cancer progression independently of MDM2/CDK4 co-amplification." (PMID 25300797, 2014). "Interestingly, knockdown of Runx2 render these invasive cancer cells sensitive to apoptotic cell death in response to glucose- and serum-deprivation." (PMID 24479521, 2014). "Our results reveal the potential of Runx2 to exert oncogenic effects in primary epithelium; however, the lack of overt carcinoma in mice suggests that additional genetic mutations are required." (PMID 24626992, 2014). "Next, we verified whether shRNA-mediated RUNX2 gene knockdown could produce any cancer-related phenotypic changes in EOC cells." (PMID 24124450, 2013). "Additionally, accumulating evidence demonstrated that the dysregulation of RUNX2 expression is frequently detectable in a variety of human cancers and higher expression level of RUNX2 is closely correlated with poor clinical outcome of the patients." (PMID 24078903, 2013). "In addition to directly regulating expression levels of BMP family members as shown by these studies, Runx2-Smad complex has been shown to regulate expression of genes related to osteogenic and cancer properties in response to TGFβ/BMP signaling." (PMID 22537242, 2012). "The phenomenon of Runx2 shuttling between the cytoplasm and the nucleus has been reported and may depend on microtubules in cancer cells." (PMID 21912699, 2011). "Given the important role of Runx2 in cancer-induced angiogenesis and metastasis, we wondered whether it plays a role in the inhibition of MMP-2 and MMP-9 expression induced by LGD1069." (PMID 21649908, 2011). "The transcription factor Runx2 has an established role in cancers that metastasize to bone." (PMID 20591170, 2010). "Additionally, there was moderate-to-strong Runx2 expression in the fibroblasts within the desmoplastic stroma surrounding the cancer cells in 11 out of 20 cases." (PMID 17876328, 2007). "Additionally, the Runx2 inhibitor decreased proliferation and enhanced apoptosis in Hepa1-6 cancer cells, suggesting that Runx2 inhibition not only improves CD8+ T-cell function but also suppresses growth in cancer cells, potentially enhancing the efficacy of immunotherapy." (PMID 41382107, 2025). "Moreover, we also revealed that G12V mutant is a stronger inhibitor of Runx2 expression than G12S, which also correlated with a stronger inhibition of osteogenesis, further proving observations from cancer studies data and clinical observations from CS patients." (PMID 40000861, 2025). "Thus, there may be a relationship among TGF‐β1, Runx2 and COL1A1 related to cancer cachexia‐associated SMF." (PMID 39091264, 2024). "Runx2 expression was found to be significantly decreased in the FS diet only, which suggests that miR-137 may be upregulated with an FS intervention and contribute to cancer-protective effects." (PMID 38059614, 2024).
cancer (continued). "However, a potentially protective role of RUNX2 in cancer has also been reported." (PMID 37108164, 2023). "Thus, upregulation of RUNX2 or FOXO1 may alternatively favor fatty acid metabolic pathways to promote cancer proliferation." (PMID 35851595, 2022). "To investigate whether the effect of RUNX2 could be extended to a broader scope of cancers, we performed tissue microarray using immunohistochemical staining to analyze the expression of RUNX2 in 6 patients with other carcinomas (i.e., thyroid, rectum, liver, and lung)”." (PMID 35534547, 2022). "In addition, increasing evidences suggested an aggressive role of Runx2 in various cancers." (PMID 33767130, 2021). "Therefore, distinct cellular localization of Runx2 may be responsible for the different functions of Runx2 during cancer progression." (PMID 33767130, 2021). "Therefore, the effects of CBX4 on Runx2 are different among cancer cell types, depending on the cellular ratio of GCN5 to HDAC3, and subsequently CBX4 may promote or inhibit metastasis depending on the cancer type." (PMID 32111827, 2020). "However, the majority of identified genes were not previously associated to RUNX2 activity in cancer, providing new details about the transcriptional program sustained by this TF in cancer." (PMID 31395086, 2019). "The upregulation of ZO-1 after downregulation of miR-196a or Runx2 is associated with reduced sphere formation and suppressed transwell invasion and transendothelial ability, indicating a critical role for ZO-1 upregulation in suppressing EMT and cancer metastasis." (PMID 31614906, 2019). "Therefore, the acquisition of RUNX2 expression by prostate cells seems to be linked to cancer transformation rather than to metastatic process." (PMID 30627063, 2018). "The role of RUNX2 in carcinogenesis and cancer progression may be tissue and context-dependent." (PMID 27007162, 2016). "However, the precise molecular mechanism(s) how RUNX2 could contribute to the initiation and progression of cancers remains elusive." (PMID 24078903, 2013). "We treated P14 CD8+ T cells to form suitable condition with either the Runx2 inhibitor or vehicle, then coculturing exhausted P14 CD8+ T cells with Hepa1‒6 gp33 cancer cells for 30 h." (PMID 41382107, 2025). "Based on the notion of “transcriptional addiction,” targeting transcription regulators, including CDK7, has emerged as a powerful strategy to attenuate cancer dependency, particularly in cancers that rely on SE-driven genes (e.g., MYC, RUNX2, SOX2, SOX9)." (PMID 39800748, 2025). "This biomechanical duality is amplified through feedforward loops with an epithelial–mesenchymal transition (EMT) and cancer stem cell (CSC) populations, mediated by signalling axes such as TGF-β/Runx2." (PMID 40243781, 2025). "In this work, we consolidated the centrality of these molecules in cancer biology demonstrating that RAIN, through multimodal activity, cooperates with RUNX2 and potentially with other TFs to orchestrate the transcriptional program supporting TC progression." (PMID 39271656, 2024). "The percentage of RUNX2+ cells was lower in cancer tissues than in paracancer tissues, while the percentage of CD103+CD8+RUNX2+T/CD8+T cells was higher in cancer tissues than in paracancer tissues." (PMID 39822248, 2024). "The oncogene overexpressions of RUNX2 and MYC generate proteins that aid in cancer cell maintenance and proliferation." (PMID 37370857, 2023). "RUNXs belong to a family of metazoan transcription factors, and there are three main RUNX in mammals (namely, RUNX1, RUNX2, and RUNX3), which are the major regulators of development and often deregulated in human cancers." (PMID 36321611, 2023).
cancer (continued). "Considering downstream regulation, WWOX inhibited the expression of RUNX2 and its target gene MMP9, reducing cancer invasiveness." (PMID 36979157, 2023). "In LC H1299 cells, inhibition of RUNX2 and its target gene MMP-9 by WW domain-containing oxidoreductase (WWOX) significantly suppressed cancer cell migration and invasion." (PMID 37766868, 2023). "RUNX2 interacted with BRG1 to form a compact complex contributing to promoter recruitment and transcriptional activation of CD44, a biomarker of cancer stem cells." (PMID 37108164, 2023). "Direct binding of RUNX2 to the MMP1 promoter region was detected, suggesting the potential significance of the RUNX2-MMP1 axis in cancer progression." (PMID 37108164, 2023). "In malignant BC tissues or cell lines with high levels of RUNX2, endogenous SIRT6 expression is lower, further supporting the role of RUNX2 in suppressing SIRT6 and promoting glycolytic metabolism conducive to cancer progression." (PMID 38203666, 2023). "It has been reported that NELFB has a synergistic effect with TCF1 in T cell response to cancer, while a non-coding RNA AK045490 inhibits osteogenic differentiation by down-regulating the expression of TCF1, LEF1 and Runx2." (PMID 38260098, 2023). "Second, SOX9 interacts with RUNX2 to induce the transcription of MYC, a known survival factor in OS and many types of cancer." (PMID 37491298, 2023). "In the present study, we first performed a pan-cancer analysis of the expression of RUNXs and then demonstrated that RUNX1, RUNX2, and RUNX3 are highly expressed in various cancers." (PMID 36321611, 2023). "RUNX2 overexpression induced COL1A1 expression and promoted cancer cell migration and invasion in vitro and in an animal model of metastasis via COL1A1." (PMID 37108164, 2023). "For the first time, we used TCGA, Oncomine, and cBioPortal to analyze the RUNX gene family (RUNX1, RUNX2, and RUNX3) in 33 distinct human cancer types and matched normal tissues." (PMID 35522574, 2022). "High significance of the runt-related transcription factor family (RUNXs), including RUNX1, RUNX2, and RUNX3, which are involved in developmental processes, immune response, and cancer, was also identified." (PMID 35629968, 2022). "Bone morphogenetic proteins (BMPs) belonging to the transforming growth factor beta superfamily can stimulate increased osteoblastogenesis by activating the runt-related transcription factor-2 (RUNX-2) and promote the growth of cancer cells at the same time." (PMID 36230816, 2022). "The transcription factor RUNX2 is another effector, which was shown to be dependent on the AKT activation in both cancer entities." (PMID 34064589, 2021). "To evaluate the potential impact of CM administration, we conducted a pan-cancer survival analysis focusing on the regulation of three genes such as MMP9, Runx2, or Snail." (PMID 34373756, 2021). "A pan-cancer survival analysis revealed that the downregulation of MMP9, Runx2 and Snail by CM had a significant impact on survival outcomes (p < 0.00001)." (PMID 34373756, 2021). "Osteomimetic features adopted by cancer cells involve the expression of bone-related molecules such as osterix, osteoprotegerin (OPG), runt-related transcription factor (RUNX2), metalloprotease (MMP) 9, MMP-13, and cathepsin K44,45." (PMID 34018387, 2021). "Meanwhile, we also analyzed the protein and mRNA expressions of RUNX2, BRG1, and CD44 in the CRC tissues and found that their protein and mRNA levels were more elevated in the CRC tissues than in the adjacent cancer tissues." (PMID 33071648, 2020). "Osteogenic transcription factors such as RUNX2, MSX2, OPG, and OPN are expressed in multiple tissues and regulate the progression of diverse diseases such as cancer, fibrosis, and bone diseases." (PMID 32375326, 2020). "Here, the authors show that the RUNX2 super-enhancer is hijacked to activate MYC in addition to RUNX2 expression, promoting the development of this cancer." (PMID 30971697, 2019).
cancer (continued). "Immunoblotting showed that RUNX2 was expressed at a high level and RUNX1 at a variable level in 11 AGCT samples from the Alberta Cancer Research Biobank." (PMID 31311113, 2019). "Therefore, lower thyroid hormone levels, which may further allow decreased signal to THRβ, might induce cancer-specific RUNX2 overexpression and finally present microcalcification specific to PTC, and mixed calcification, which consists of accumulated and combined microcalcifications." (PMID 30049993, 2018). "Considering the oncogenic role of miR-23a, the promotion of miR-23a expression by Runx2 plays a carcinogenic role in mouse HCC cells, as it does in several cancer types, including ovarian, breast, liver and prostate cancer." (PMID 29743543, 2018). "Thus, RUNX2 might be a potential therapeutic target in Rg1-mediated angiogenesis in cancer." (PMID 28938538, 2017). "FOSL1, BCL2, CDK6, IL7R, RUNX2 and CDC25B have been shown to be targets of JQ1 for transcriptional silencing in other types of cancers." (PMID 27764802, 2016). "In this review, we are focusing on the functional interrelations between RUNX2 and the PI3K/AKT pathway, which contribute to cancer progression." (PMID 26204939, 2015). "In this review, we address the interaction of RUNX2 with the PI3K/AKT signaling pathway, one of the critical axes controlling cancer growth and metastasis." (PMID 26204939, 2015). "In the context of cancer cells, constitutive AKT activation would favor FOXO1/O3 nuclear exclusion, thereby decreasing RUNX2 ubiquitination and degradation and increasing RUNX2 stability." (PMID 26204939, 2015). "Several key biological pathways are enriched for cancer-specific sets of isoTWAS-prioritized genes, including cell cycle and mitosis regulation, DNA and RNA binding, immune pathways, as well as downstream targets of cancer-relevant transcription factors like ESR1, RUNX2, and YY1." (PMID 40775447, 2025). "Although at present no MGP- or RUNX2-specific inhibitors have been approved for cancer treatment, these molecules are under active investigation as potential therapeutic targets." (PMID 39684309, 2024). "This study also showed a positive correlation between the expression levels of the cancer-related transcription factor Runx2 and OPN in 55 patients and a negative correlation in 50 patients." (PMID 38887353, 2024). "The first were tightly regulated, through MELK, BRCA2, KIF14, BUB1, and TOP2A, by five TFs (NFE2L3, RUNX1, RUNX2, BHLHE40, and the aging cancer-specific SOX11), two LncRNAs (ST7OT1 and CDKN2BAS), and four miRNAs (miR-21-5p, miR-363-3p, miR-873-5p, and miR-138-1-3p)." (PMID 37191407, 2023). "RUNX2 also promotes metastasis by activating the AKT/PI3K, YAP-TAZ, TGFβ, and WNT signaling pathways and angiogenesis, thereby driving positive feedback loops that advance cancer progression." (PMID 37190015, 2023). "RUNX2 is a transcription factor involved in the differentiation of human osteoblasts; it is activated by multiple signaling pathways, including PI3K/AKT and NF-κB, and plays a role in bone metastasis of different cancer types, including breast cancer." (PMID 37759706, 2023). "The immunoreactivity of Runx2 was observed in both carcinoma cells and stromal cells, as well as non-pathological ductal cells." (PMID 37759471, 2023). "Besides, miR-485-3p has been also proved to be involved in the cancer development via regulating TGF-β pathways, and RUNX2 has been widely confirmed as the downstream factors of TGF-β." (PMID 35340229, 2022). "The direct involvement of RUNX2 in tumorigenesis has been rarely reported, while the function of RUNX2 in regulating epithelial to mesenchymal transition (EMT) and drug resistance in cancer has been recently reported." (PMID 36429115, 2022). "Here, we confirmed that RUNX2 could recruit the NuRD(MTA1)/CRL4B complex to induce cell proliferation, invasion, tumorigenesis, and bone metastasis, as well as cancer stemness." (PMID 35534547, 2022).